CD4 (CD4 molecule)
Diseases named in the same sentence as CD4 in open-access papers (continued):
Sharing a sentence is not in itself a finding about the gene and the disease.
infectious disease (continued). "Also, the level of the Th1 cytokine IFN-γ released by CD4+ T-cells in the spleen was enhanced after immunization with SyBVS1, strongly suggesting that SyBV can be a universal vaccine platform for various infectious diseases, including viruses." (PMID 37208676, 2023). "It has been hypothesized that these CD4 T effector clusters (especially effector memory CD4 T cells), possibly produced through repeated antigen stimulation, might play an important protective role against infectious diseases (e.g., Mtb)." (PMID 37435066, 2023). "Therefore, these genotypes and their association with higher levels of CD4+ and CD8+ T cells could be attributed to the host being genetically resistant to infectious diseases." (PMID 34573362, 2021). "The quality of CD4+ T-cells in smokers has been significantly affected and this defect in their immune function could explain why smokers develop serious complications during an infectious disease." (PMID 24842313, 2014). "In this context, we posit that the involvement of STAT3 activation in pathogenic mechanisms of autoimmune and infectious diseases may not be confined to CD4+ T cells." (PMID 24204098, 2013). "Infectious disease-trained physicians were more likely to defer therapy than providers without specialty training (OR 2.2; 1.4-3.46), an association not observed at lower CD4+ counts." (PMID 22360788, 2012). "The most recent concerns regulatory T (Treg) cells, a subset of CD4+ cells suppressing immune responses to maintain unresponsiveness to self-antigens and prevent excessive immune responses to foreign antigens, which play an important role in autoimmune and infectious diseases." (PMID 22745730, 2012). "This novel TCR-independent and therefore antigen-non specific mechanism for by-stander CD4+CD25hiFoxp3+ cell induction is likely to reflect a process also occurring in vivo as a consequence of immune activation during malaria infection, and potentially a range of other infectious diseases." (PMID 19680449, 2009). "The induction of CD4+ and CD8+ T cells has been shown to be central to effective T cell immunity in infectious diseases." (PMID 40533467, 2025). "Cellular immunity, mediated by both CD4+ and CD8+ T cells, plays an essential role in protecting against infectious diseases and their outcomes." (PMID 38456681, 2024). "At day 3, upregulated DEGs were enriched in pathways involved in virus sensing (infectious disease: RNA virus and infectious disease: viral), and PRR signaling (NOD-like receptor, C-type lectin receptor and RIG-I- like receptor signaling) in CD4+ cells." (PMID 37920474, 2023). "Overall, these studies support the involvement of CD4+ T cells, and more specifically of CD4+ TRM cells, in the development of CD8+ TRM cells during infectious diseases." (PMID 37545498, 2023). "Particularly, Host interactions of HIV factors, HIV infection, HIV life cycle, Infectious Disease and Cellular responses to external stimuli, were enriched in DEGs of REDUC CD4 cells after RMD only and in BCN02 PBMC from individuals undergoing Vacc+RMD." (PMID 35325780, 2022). "On the other hand, patients with infectious diseases such as HPV, Treponema pallidum (TP), and aspergillus infection showed significantly lower function of CD4+ and CD8+ T cells than healthy controls." (PMID 31857499, 2019). "Furthermore, the link established here between TNF and the development of BM CD4+ T cells with potential to irreversibly impact on LT-HSC function may be of importance in other non-infectious diseases where TNF production and hematological abnormalities co-exist." (PMID 28671989, 2017). "Here, we have employed an established infectious disease model to directly compare and contrast the in vivo CTL function of antiviral CD4+ and CD8+T cell populations." (PMID 23565245, 2013). "Extrathymic CD4+CD8+ double-positive (DP) T cells are increased in some pathophysiological conditions, including infectious diseases." (PMID 21858238, 2011).
infectious disease (continued). "Following the observation that the gp120 monomers bound to cell-surface CD4 displayed the CD4i epitope, we obtained serum samples from the VaxGen Inc phase III clinical trial now licensed to the Global Solutions for Infectious Diseases." (PMID 18833294, 2008). "Conventional vaccines afford protection against infectious diseases by expanding existing pathogen-specific peripheral lymphocytes, both CD8 cytotoxic effector (CTL) and CD4 helper T cells." (PMID 15588284, 2004). "CD4+ and CD8+ T cell memory play a pivotal role in combating infectious diseases." (PMID 40723393, 2025). "Several studies showed that DM patients often may present immune impairment, particularly concerning reduced levels of T lymphocyte (both CD4+/CD8+) and Natural Killer lymphocytes, suggesting decreased host defense to infectious diseases." (PMID 38630321, 2024). "Cachexia in infectious disease is proposed to be effectuated by cytokines that stimulate the NF-kB and JAK-STAT signalling pathways activation, thereby inducing various catabolic pathways in adipose tissue and muscles which favours CD4+ T cell reprogramming." (PMID 38055777, 2023). "Despite major genetic losses within the CD4+ pathway and the limited response of specific antibody upon immunisation, in its natural environment cod is not particularly prone to infectious diseases." (PMID 33154745, 2020). "The direct role of NLRC3 in the modulation of CD4+ T-cell responses in infectious diseases has not been studied." (PMID 30133544, 2018). "However, the ability of NLRC3 to modulate CD4+ T cell responses and the mechanisms by which NLRC3-mediated control of T cells can affect infectious disease progression remains poorly defined." (PMID 30133544, 2018). "Additionally, CD4-independent CD8+ T cells responses have been observed in tumors and several infectious diseases." (PMID 24805101, 2014). "Still, in settings of infectious diseases and vaccination, most studies have focused on CD4+ regulatory T cells, and not CD8+ regulatory T-cells." (PMID 24714620, 2014). "These diseases are both communicable diseases and opportunistic diseases, meaning that they are frequent in the general population, more frequent in HIV-infected patients, and of increasing incidence with decreasing CD4 count." (PMID 24373303, 2013). "Our study shows that among African HIV-1 serodiscordant couples, who likely share many determinants of health such as socioeconomic status, nutrition and infectious disease exposures, mortality was higher in the HIV-1 infected partner at all but the highest levels of CD4 cell count (>500 cells/μl)." (PMID 23130818, 2012). "An infectious diseases doctor was frustrated over the limited routine healthcare services at the hospital on the weekends and suggested that the Determine LAM test, together with CD4 cell count, should be accessible at all times and part of a POC package for patients with advanced HIV." (PMID 38249371, 2023). "This type of peripheral tolerance is distinct from and likely complementary to the one mediated by CD4+ Tregs, which represent a separate lineage of T cells and do not appear to be generally active in the human infectious diseases analyzed here or in murine infections." (PMID 35258337, 2022). "Consequently, the increase in both CD4+ and CD8+ T cells in this case, as previously reported in other infectious diseases, may play a similar antiviral role with respect to the improvement in the disease." (PMID 32399213, 2020). "However, the direct role of NLRC3 in modulation of CD4+ T-cell responses in infectious diseases has not been studied." (PMID 30133544, 2018). "This property is also extremely attractive where an established vaccine platform/regimen generating mixed CD4 and CD8 T cells could be rapidly adapted and deployed to serve as a component of a public health emergency response to control an emerging infectious disease outbreak." (PMID 27466350, 2016).
infectious disease (continued). "IL-2 has been recently linked to improved secondary proliferation, while the role of IL-7 in maintenance of CD4+ memory cells has been demonstrated in homeostatic proliferation, but its role in protective memory populations in infectious disease protective has not been fully investigated." (PMID 22039531, 2011). "Therefore, utilizing a CD4+T cell cytokine profile may indeed aid in predicting CD8+T cell responses in specific scenarios, such as emerging infectious diseases or the characterization of novel complex multi-antigenic vaccines or in immunocompromised patients with low cell count." (PMID 39104410, 2024). "Our study provides a dynamic landscape of lymphocytes and demonstrates a systemic investigation of CD4+ CTL effects infiltrating into OSCC lesions, which may share some pathogenesis reported in severe T and B cell-activated diseases such as autoimmune and infectious diseases." (PMID 38077321, 2023). "Finally, consultations within the category need for further testing or laboratory results before starting or amending a current treatment most commonly included the subthemes of high-risk patient setting, medication non-compliance, other chronic or infectious diseases, and low CD4 count." (PMID 32866154, 2020). "Furthermore, CD4 GPR56+ TEMRA cells with cytotoxic potentials may have an important function in eliminating infected cells and may be highly relevant in vaccine-elicited protection against infectious diseases." (PMID 29133794, 2017).
inflammation (180 papers, 1995 to 2026). Aberrant reaction of the microcirculation characterized by movement of fluid and leukocytes from the blood into extravascular tissues. "During the progression of pulmonary inflammation and fibrosis caused by silica, the CD4+ cell subsets played a vital role." (PMID 37828528, 2023). "Recent findings suggest that pathogenic CD4+RORγt+ cells contribute to brain inflammation and neurobehavioural disorders." (PMID 37108638, 2023). "Having determined that Cul5 deficiency in CD4+ T cells predisposes mice to Th9-mediated lung inflammation, we next wanted to assess how Cul5 functions in CD4+ T cells." (PMID 35589717, 2022). "IL-2 deletion in CD11chighMHCII+ DCs caused more severe, spontaneous intestinal inflammation in Il2CD11c mice compared to Cnb1CD11c mice, which was characterized by expansion of activated CD4+ effector T cells and substantial reduction of Treg cells." (PMID 29549257, 2018). "Because CCR4 induces the recruitment of regulatory T cells to the lung, we used CCR4-deficient (CCR4−/−) mice as a tool to address the role of CD4+Foxp3+ T cells in the chronic lung inflammation induced during M. tuberculosis infection." (PMID 30584243, 2018). "As such, identification of Eomes+ CD4+ T cells as pathogenic lymphocytes in chronic CNS inflammation has a major implication in understanding the chronic CNS inflammation and designing a novel effective therapy for SPMS." (PMID 26436530, 2015). "The CD4+ T cells cause the aggravation of chronic airway inflammation by producing IL-17." (PMID 37836429, 2023). "Collectively, these data indicate that iNKT cells play a critical role in regulating Foxp3 expression by CD25+CD4+ T cells and thereby determine the fate of these CD25+CD4+ T cells into either protective or pathogenic ones during DSS-induced intestinal inflammation." (PMID 36499642, 2022). "Foxp3+CD4+ regulatory T cells are instrumental in enforcing homeostasis at the intestinal barrier surface as illustrated by the development of intestinal inflammation in diseases caused by a primary deficiency in the number or function of Treg cells in the gut." (PMID 34262567, 2021). "Whereas CD4+Foxp3+ cells regulate inflammation-mediated tissue damage, this aspect has not been addressed during chronic tuberculosis, the hallmark of which is the perpetuation of lung inflammation." (PMID 30584243, 2018). "We hypothesized that penile inflammation may increase HIV susceptibility in men by recruiting permissive CD4 T cells, and that male circumcision may decrease HIV susceptibility in part by reducing genital inflammation." (PMID 27898732, 2016). "Our previous work revealed that conditional PKCλ/ι knockout in CD4+ T cells alleviates S. japonicum-induced hepatic granulomatous inflammation and fibrosis by suppressing Th2 polarization and IL-4+ CD4+ T-cell expansion." (PMID 41154658, 2025). "Given the different roles of different CD4+T cell subsets in silicotic fibrosis, regulating the immune balance between different CD4+T cell subsets plays an important role in alleviating lung inflammation and fibrosis." (PMID 40433386, 2025). "Using a fungal allergen (Alt)–induced allergic lung inflammation model, we observed that CD4-specific deletion of the IP receptor in CD4 T cells exacerbated pulmonary inflammation." (PMID 40587812, 2025). "To analyze the CD4/CD8 ratio in the development of spontaneous intestinal inflammation, we determined the changes in the spleen and the whole colon tissue by flow cytometry." (PMID 40004018, 2025). "Intestinal inflammation and peripheral recruitment of intestinal CD4+ cells result in an imbalance in the distribution of lymphocyte population in the blood." (PMID 39449004, 2024). "Based on these findings, we next determined if AR signaling in CD4+ T cells attenuated HDM-induced airway inflammation and modified expression of metabolites in CD4+ T cells." (PMID 39404231, 2024).
inflammation (continued). "Eomes expression in CD4+ T cells has been found in mouse models of chronic inflammation and inflammatory disorders in human, but its specific functions remain astonishingly unclear." (PMID 36756120, 2023). "The results of the present study have provided evidence that B cells in tuberculous WT C57BL/6 mice with chronic TB can promote lung granulomatous inflammation in a CD4+ T cell-dependent and IL-10-dependent manner." (PMID 36888692, 2023). "In liver inflammation, IL-17 is mainly produced by CD4+ T (TH17) and CD8+ T cells (Tc17), although numerous other cells (macrophages, natural killer cells, neutrophils and Tγδ cells) also contribute to the production of IL-17." (PMID 36836776, 2023). "The biological material used for this study came from fecal pellets of three mice of two different strains—two wild-type C57BL/6N mice and a transgenic CD4-dnTβRII (DNR) mouse prone to developing intestinal inflammation." (PMID 35417481, 2022). "CD4+ T-cell responses were investigated in the model of anti-CD3 mAb-induced intestinal inflammation, which allows analysis of Th1, Th17, Treg, and Tr1-cell differentiation." (PMID 35095852, 2021). "Severe lung inflammation occurs in mice with a Runx1-deleted Bcl2-transgenic (which was introduced to improve CD4 cell survival) naïve CD4 T cells." (PMID 34421907, 2021). "To further explore the role of Th17 cell-derived TGF-β1 in the regulation of Th17 stability and pathogenicity in different inflammatory settings, we employed an animal model of CD4+ T cell-mediated intestinal inflammation." (PMID 34050263, 2021). "Secreting IFN-γ to induce the differentiation of naive CD4+ T cells into Th1 cells had been considered for TCs to improve allergen-induced airway inflammation and hyper-responsiveness." (PMID 32028987, 2020). "In summary, our data demonstrated for the first time that dysregulated Tfh cells, a new type of CD4+ T cells, contribute to retinal vascular inflammation in DR." (PMID 32226551, 2020). "The essential contribution of CD4+ T cells in allergic airway diseases has been demonstrated, especially by using various murine models of antigen-induced airway inflammation." (PMID 33050549, 2020). "Ratios between 1.5–2.5 are generally considered normal, and a low or inverted CD4/CD8 ratio is associated with altered immune functions such as seen in infections and chronic inflammation." (PMID 30759167, 2019). "Schistosome eggs elicit a CD4+ Th cell-mediated hepatic granulomatous inflammation, which is the major pathological consequence of the disease." (PMID 29899232, 2018). "Of these cells, monocytes undergo the most prolonged retention and migration in the glomerular capillaries and are required for CD4+ T-cell-mediated induction of neutrophil-dependent glomerular inflammation." (PMID 29467472, 2018). "In the era of ART, signs of chronic systemic inflammation are observed in a large number of patients, even when blood viral load is undetectable and CD4+ T cell counts are restored to preinfection levels." (PMID 28811349, 2017). "Very recently, it has been shown that CD4+-T cells contribute to age-related myocardial inflammation and functional decline in aged mice." (PMID 29167489, 2017). "Cats dually sensitized to both Bermuda grass allergen and house dust mite given AIT to either allergen displayed decreased eosinophilic airway inflammation and higher levels of CD4+ CD25+ FoxP3+ Treg cells compared to placebo-treated cats." (PMID 28056956, 2017). "By adoptive transfer of AvCystatin-primed peritoneal exudate cells we were able to induce IL-10 producing CD4 T cells and ameliorate airway inflammation." (PMID 27560829, 2016). "It is not clear if this reduction in the number of T cells at early stages of airway inflammation correlates with a regulatory T-lymphocyte phenotype (CD4+ CD25+ FoxP3+) in a model of pathogen-mediated inflammation in the colon." (PMID 27795621, 2016).